PINK1 (PTEN induced kinase 1)
Diseases named in the same sentence as PINK1 in open-access papers (continued):
Sharing a sentence is not in itself a finding about the gene and the disease.
ovarian carcinoma (continued). "Our study showed a dramatic increase in the number of mitochondria and a significant down-regulation of PINK1 expression in curcumin-treated ovarian cancer cells, suggesting that the accumulation of dysfunctional mitochondria might be due to a decrease in mitochondrial autophagy." (PMID 40163489, 2025). "Moreover, mitochondria were isolated from endothelial cells in different intervention groups and Western blot revealed that IDO1high ovarian cancer cell-derived EVs upregulated the expression of PINK1 and Parkin, which are classical markers of the mitophagy-associated pathway." (PMID 38468343, 2024). "PINK1 knock-out mice could be applied to construct new ovarian cancer models." (PMID 37940999, 2023). "A recent pan-cancer analysis indicated that PINK1 mRNA expression was lower in several cancer groups than in normal tissues, including the brain, breast, colorectal, oesophageal, head and neck, liver and ovarian cancers, as well as leukemia and melanoma, and higher in diffuse large B-cell lymphoma." (PMID 37047483, 2023). "Furthermore, the use of in vivo xenograft models revealed that PINK1 knockdown could inhibit abdominal metastasis and chemotherapy resistance of ovarian cancer." (PMID 37940999, 2023). "In ovarian cancer, PINK1 can phosphorylate PTEN at Ser179, thereby promoting ovarian cancer metastasis and chemotherapy resistance by regulating PTEN." (PMID 41299664, 2025). "The PINK1 and PRKN enrichment was observed with the conversion of LC3-I to LC3-II in the mitochondrial fraction of pyrimethamine-treated ovarian cancer cells in a dose-dependent manner." (PMID 40918465, 2025). "Our data showed thatCLPP knockdown promoted the expressions of PINK1, Parkin, and LC3II/I proteins in wild-type ovarian cancer cells, while CLPP overexpression decreased these levels of expression." (PMID 38419499, 2024). "Therefore, PINK1 might be a novel therapeutic target for ovarian cancer treatment." (PMID 37940999, 2023). "We further validated the interaction between endogenous PINK1 and PTEN in ovarian cancer cells using co-IP with an anti-PINK1 or anti-PTEN antibody in A2780 and SKOV3 cell lines." (PMID 37940999, 2023). "We also found that PINK1 phosphorylates PTEN at Ser179, thereby regulating its nuclear localization and activating AKT in ovarian cancer." (PMID 37940999, 2023). "Further IF analysis in A2780 and SKOV3 cells confirmed the interaction between endogenous PINK1 and PTEN in ovarian cancer cells." (PMID 37940999, 2023). "PINK1 (PTEN-induced putative kinase 1) gene was first outlined by Unoki and Nakamura in 2001, who described its role in the pathogenesis of ovarian cancer." (PMID 34831247, 2021). "We discovered that the upregulation of the LC3II/LC3I ratio and the expression of PINK1 and Parkin could be inhibited by HCQ, further proving that ovarian cancer cell-derived EVs could trigger the mitophagy in endothelial cells." (PMID 38468343, 2024). "Since Parkin expression is extremely low in ovarian cancer, we focused on exploring the function of PINK1 in the absence of Parkin." (PMID 37940999, 2023). "Our findings revealed a correlation between PINK1 and a negative prognosis for ovarian cancer patients based on open database and our own local cohort." (PMID 37940999, 2023). "PARK6 (PINK1) is also known to play a role in breast and ovarian cancers." (PMID 36788297, 2023). "In conclusion, our study identified PINK1-PTEN axis promotes ovarian cancer through non-canonical pathway independent of Parkin." (PMID 37940999, 2023). "In our future projects, genetic animal models, patient-derived xenografts models, and organoid models, may help to further understanding the impact of PINK1-PTEN axis on ovarian cancer and determine more effective treatments for ovarian cancer patients." (PMID 37940999, 2023).
ovarian carcinoma (continued). "PTEN-induced putative kinase 1 (PINK1) is a key mediator of mitochondria quality control induced by the tumor suppressor gene PTEN, whose expression levels decline in more aggressive ACCs and in ovarian cancer." (PMID 29520253, 2018). "PINK1 could up-regulate the activity of AKT and inhibit PTEN nuclear translocation by phosphorylating PTEN at Ser179, which eventually promote the metastasis and chemotherapy resistance of ovarian cancer." (PMID 37940999, 2023). "Additionally, a meta-analysis conducted on human ovarian cancer patients indicated that a high PINK1 mRNA expression is correlated with a negative prognosis." (PMID 37940999, 2023). "However, we do not exclude the possibility of a correlation between PINK1 and metastasis to other sites in ovarian cancer, as the positive correlation may be masked due to the limited number of patients in the cohort." (PMID 37940999, 2023). "For both OV (ovarian cancer) and TGCT (testicular germ cell tumor), PINK1 significantly influenced RFS but not OS (RFS: log-rank P = 0.022; RFS: log-rank P = 0.011)." (PMID 33244455, 2020).
Hyperglycemia (22 papers, 2017 to 2026). An increased concentration of glucose in the blood. "Seahorse assay showed that Pink1 deficiency aggravated hyperglycemia-induced decreases in basal and maximal oxygen consumption rates, which are indicators of mitochondrial dysfunction." (PMID 37928264, 2023). "PINK1 deficiency was also associated with exaggerated hyperglycemia-induced mitochondrial dysfunction and defective mitophagic activity, whereas PINK1 overexpression ameliorated these negative effects and restored mitochondrial homeostasis." (PMID 37928264, 2023). "PINK1 deficiency accelerated hyperglycemia-induced mitochondrial fission in the renal tubular cells of diabetic mice." (PMID 37928264, 2023). "Our RNA sequencing analysis showed the decreased expression level of Drp1 in osteoblasts cultured in high glucose medium, suggesting the potential interplay between Drp1 and PINK1-induced mitophagy in impaired osteogenic differentiation caused by hyperglycemia." (PMID 39758822, 2025). "Moreover, the causality between renal PINK1 expression and sustained hyperglycemia remains uncertain." (PMID 37928264, 2023). "Interestingly, we observed that hyperglycemia-treated and/or PINK1-deficient HKC-8 cells exhibited increased levels of phospho-RIPK1 at S161 and S166, respectively, both of which were involved in necroptosis initiation 26,48." (PMID 37928264, 2023). "Knockdown of PINK1 promoted profibrotic phenotypes in renal tubular epithelial cells associated with hyperglycemia-induced mitophagic activation suppression and an increase in intracellular ROS, whereas Pink1 overexpression significantly ameliorated these negative effects." (PMID 37928264, 2023). "Notably, hyperglycemia-associated elevations in phospho-RIPK1 levels were augmented by PINK1 deficiency." (PMID 37928264, 2023). "In this cycle, hyperglycemia impairs both the PINK1/Parkin-mediated mitophagy pathway and ubiquitin-independent pathways like FUNDC1 under hypoxic conditions, leading to the accumulation of damaged mitochondria." (PMID 41793088, 2026). "A previous study demonstrated that PINK1/Parkin-mediated mitophagy alleviated mitochondrial dysfunction in DM rats, thus protecting endothelial cells from hyperglycemia-induced damage." (PMID 40308774, 2025). "Our research demonstrates that hyperglycemia-induced mitochondrial dysfunction, especially characterized by impaired PINK1-Parkin-dependent mitophagy, is significantly mitigated by canagliflozin treatment." (PMID 39000117, 2024). "Hyperglycemia dramatically inhibited mitophagy in HUVECs by downregulating PTEN-induced kinase 1 (PINK1), Parkin, LC3 II, Beclin-1, and autophagy-related gene 5 (ATG5)." (PMID 38645427, 2024). "Hyperglycemia upregulated the expression of PINK1 and profibrotic markers in these cells, which is consistent with our in vivo data." (PMID 37928264, 2023). "In contrast, hyperglycemia-induced mitophagic dysfunction was successfully rescued by Pink1 overexpression." (PMID 37928264, 2023). "In contrast, Pink1 overexpression significantly attenuated hyperglycemia-induced phenotypic changes in HKC-8 cells." (PMID 37928264, 2023). "Consistently, in vitro experiments demonstrated that Pink1 depletion augmented hyperglycemia-induced overproduction of mitochondrial and cellular ROS, whereas its overexpression ameliorated ROS generation in HKC-8 cells." (PMID 37928264, 2023). "To determine the effect of PINK1 deficiency on DKD in vivo, we first induced hyperglycemia in Pink1+/+ and Pink1-/- mice through STZ injection." (PMID 37928264, 2023). "First, we found that hyperglycemia induced podocyte injury and PINK1/Parkin-mediated mitophagy inhibition in the cell experiments." (PMID 36902127, 2023). "For instance, mesenchymal stem cells alleviate hyperglycemia-mediated endothelial damage via Pink1/Parkin-independent mitophagy." (PMID 35068334, 2022).
Hyperglycemia (continued). "Taken together, these results exhibit a new mechanism by which HIF-1α protects against hyperglycemia-induced oxidative injury and enhances mitophagic activity, at least partially via Parkin/PINK1 signaling pathway in tubular cells." (PMID 35186974, 2021). "In summary, our results demonstrated that MSCs treatment attenuates hyperglycemia-induced endothelial injury through the mitophagy-mediated removal of dysfunctional mitochondria, in which the Pink1/Parkin pathway plays a critical role." (PMID 30082798, 2018). "Taken together, we hypothesized that PINK1/Drp1-mediated mitophagy plays a critical role in osteogenic differentiation, and its suppression contributes to hyperglycemia-induced impaired osteoblastogenesis." (PMID 39758822, 2025). "Similarly, in hyperglycemia-induced tubular cell damage, Nrf2 enhances mitochondrial quality by facilitating mitophagy through PINK1/Parkin, reducing ROS accumulation and protecting cells from injury." (PMID 39860131, 2025). "The hyperglycemia-induced mitochondrial stress was ameliorated by Pink1 overexpression." (PMID 37928264, 2023). "Moreover, Pink1 overexpression significantly attenuated hyperglycemia-induced upregulation of these cytokines, and the restoration of mitochondrial integrity and suppression of ROS production accompanied these beneficial effects." (PMID 37928264, 2023). "Moreover, the restoration of PINK1 expression was found to reverse the cellular stresses induced by hyperglycemia, highlighting its significance in mitigating these adverse effects on podocytes." (PMID 37928264, 2023). "Furthermore, the role of PINK1 accumulation in the mitochondrial outer membrane under hyperglycemia and recruitment of Parkin as well as Drp1 activation need to be investigated further." (PMID 28492550, 2017). "Phosphatase and tensin homolog- (PTEN-) induced kinase 1 (PINK1)/Parkin pathway, which is normally involved in the clearance of dysfunctional mitochondria, is also required for infused MSCs to restore mitophagy pathways in hyperglycemia-challenged endothelial cells." (PMID 32724315, 2020).
Cerebral ischemia (20 papers, 2016 to 2026). Restriction of arterial blood supply to the brain associated with insufficient oxygenation to support the metabolic requirements of the tissue. "Similarly, enhancing Parkin /PINK1-mediated mitophagy could inhibit apoptosis caused by cerebral ischemia/reperfusion injury in hippocampal neurons." (PMID 33424757, 2020). "Several studies have reported that activating the PINK1/Parkin pathway in acute cerebral ischemia models can improve mitochondrial function and alleviate neuron damage." (PMID 40016173, 2025). "Early in brain ischemia, mitochondrial dysfunction triggers a series of changes, with the PINK1/Parkin pathway playing a key role in this process." (PMID 41317220, 2025). "TOM7 can modulate autophagy through the PINK1/Beclin 1 signaling after cerebral ischemia, and silencing TOM7 inhibits autophagy via the PINK1/Beclin 1 pathway to aggravate cerebral ischemia." (PMID 37856037, 2024). "However, PINK1 deficiency and midivi-1 (a mitochondrial division inhibitor) further exacerbated ischemia-induced brain damage, mitochondrial dysfunction, and neuron injury, thereby eliminating the enhanced mitochondrial autophagy under cerebral ischemia-reperfusion injury." (PMID 38650626, 2024). "PINK1/Parkin-mediated mitophagy is also activated in brain damage induced by cerebral ischemia and reperfusion." (PMID 34168551, 2021). "Of these pathways, PINK1/Parkin-dependent mitophagy was of special concern in the progress of multiple neurological diseases, especially cerebral ischemia." (PMID 34145219, 2021). "Moreover, miR-361-3p alleviates cerebral ischemia–reperfusion injury by targeting NACC1 through the PINK1/Parkin pathway." (PMID 41446787, 2025). "Additionally, research has demonstrated that, metformin can reduce brain ischemia–reperfusion injury in animal models by activating AMPK/ULK1/PTEN-induced putative kinase 1 (PINK1)/E3 ubiquitin-protein ligase parkin (Parkin)." (PMID 40259102, 2025). "It has been found that mitophagy activated by cerebral ischemia-reperfusion may rely on the PINK1/Parkin pathway at the early stage." (PMID 37856037, 2024). "Furthermore, PINK1/Parkin pathway plays a vital role in the interplay between hypoxia-related mitophagy and cerebral ischemia." (PMID 34145219, 2021). "Notably, PINK1/Parkin pathway has been arisen extensive attention in exploring the interplay between hypoxia-related mitophagy and cerebral ischemia." (PMID 34145219, 2021). "In addition, a large body of evidence has demonstrated the critical role of PINK1/Parkin-dependent mitophagy under in vivo pathological conditions such as cerebral ischemia." (PMID 34145219, 2021). "And inhibition of PINK1/Parkin-mediated mitophagy could reduce the number of apoptotic cells in the cortex of the model group in cerebral ischemia/reperfusion injury." (PMID 33424757, 2020). "Moreover, PINK1/Parkin-induced mitophagy is protective for the hippocampus in vivo and in vitro against cerebral ischemia, which mainly arises from the suppression of oxidative stress, alleviation of neuronal apoptosis, and improvement of mitochondrial function." (PMID 34145219, 2021). "Therefore, in the early stage of cerebral ischemia, the PINK1/Parkin signaling pathway can be activated to regulate mitophagy and reduce the damage of hippocampal neurons, which might be the potential target for TEAS to improve the cognitive function in VD rats." (PMID 35692579, 2022). "Furthermore, observations like aggregation of α-Syn and depletion of proteins like DJ-1, PINK1, and Parkin after cerebral ischemia suggest that the mechanisms that are known to promote pathology in chronic conditions might also contribute to neuronal death after stroke." (PMID 28273718, 2017). "What are the roles of PINK1 and FUNDC1 in the process of cerebral ischemia?" (PMID 27554669, 2016).
depression (20 papers, 2017 to 2026). "Neuroinflammatory processes, particularly glial activation, dysregulation of PTEN-induced putative kinase 1 (Pink1) and Nrf2 pathways, and cytokine release, have been strongly associated with the development of anxiety and depression after ICH." (PMID 39851502, 2025). "In animal models, it is demonstrated that PINK1 deficiency decreases the threshold for chronic stress‐induced depression, indicating that defective mitophagy is linked to the pathogenesis of depression." (PMID 38334212, 2024). "In fact, the increased activation of mitochondrial fission by the pDRP1 Ser616 is associated to the PINK1-mediated mitochondrial quality control in resilient animals, potentially preventing the onset of major depression abnormalities." (PMID 35228511, 2022). "It has been reported that psychiatric symptoms such as anxiety and depression are more prominent in PINK1-linked PD." (PMID 33192488, 2020). "This is supported by strong correlations between PINK1 expression and stress hormones (corticosterone: r = 0.879; adrenaline: r = 0.881), as well as evidence that PINK1-deficient mice are more vulnerable to corticosterone-induced depression." (PMID 40969342, 2025). "Some studies have reported that low PINK1/Parkin levels and the subsequent mitophagy inhibition may be important pathogenic factors for depression." (PMID 38334212, 2024). "Specifically, we investigated whether PINK1 deficiency predisposed mice to basal or stress-induced depression." (PMID 33805219, 2021). "Mitochondrial and AHN defects in PINK1-deficient alone were insufficient to cause depression." (PMID 33805219, 2021). "Model rats exhibited excessive mitochondrial ROS (mtROS) accumulation, suppressed PINK1/Parkin-mediated mitophagy, neuronal injury, and anxiety- and depression-like behaviors." (PMID 42238570, 2026). "A mouse model of human depression and insomnia revealed damage to mitochondrial autophagy, decreased synthesis and secretion of melatonin, and elevated levels of IL-1β, NF-κB, Pink1, and Parkin in the pineal gland." (PMID 40943622, 2025). "The IP6K2 gene was linked to worse clinical progression, particularly higher depression levels in prodromal cases, and is known for its neuroprotective role in preventing PTEN-induced kinase 1 (PINK1)-mediated mitophagy in the brain." (PMID 40542411, 2025). "Of note, lower PINK1 levels were observed in PD patients with comorbid depression and anxiety in the PDs group." (PMID 38711597, 2024). "Our results showed that LPS-treated N9 microglia indicated lower expression of PINK1 and Parkin, which is consistent with recent study of patients with major depressive disorder." (PMID 36615696, 2022). "It has been reported that monogenic PD patients with mutations in the α-synuclein, LRRK2, VPS35, Parkin, PINK1, DJ-1 and GBA genes exhibit psychiatric disturbances such as depression and anxiety." (PMID 34145553, 2021). "In particular, PD patients carrying parkin, PINK1 and GBA mutations have more severe depression compared with idiopathic PD." (PMID 34145553, 2021). "Moreover, the levels of PINK1 were significantly lower in the PDs patients with hypertension, depression, and anxiety." (PMID 38711597, 2024). "Patients with depression might experience impaired mitochondria clearance, seen through higher PINK1, P62, and LC3B levels in peripheral blood nuclear cells, and lower Parkin levels." (PMID 37869512, 2023). "Aberrant expression of the mitophagy marker PINK1 and related proteins in individuals with clinical depression underscores that mitophagy failure could potentially serve as a causal factor for MDD." (PMID 37869512, 2023). "The mental symptoms of PINK1 monogenic PD are more frequent, including anxiety and depression." (PMID 33192488, 2020). "Both patients show mild autonomic failure (e.g. constipation), but no dementia, and no depression or anxiety, which are occasionally recognized as a non-motor symptom of PINK1-associated PD." (PMID 28438176, 2017).
depression (continued). "Thus, the dysregulation of the PINK1/Parkin signaling pathway plays a key role in the onset and progression of depression, and the enhancement of PINK1/Parkin-mediated mitophagy may be a novel means of alleviating depression." (PMID 40497971, 2025). "Notably, melatonin analogs contribute to the restoration of mitophagy and amelioration of behavioral abnormalities associated with cognitive deficits through the activation of the AMPK/PINK1 signaling pathway, which offers a new potential strategy for the treatment of depression." (PMID 40497971, 2025). "Interestingly, although PINK1 mutation carriers are clinically indistinguishable from Parkin mutation carriers, frequency of depression is higher in PINK1 carriers, calling for more detailed anatomical comparisons between these two diseases." (PMID 28458632, 2017).